GOLGA6C (golgin A6 family member C)
Tractability: No criterion of Open Targets' tractability assessment is met for any kind of drug.
Gene: Protein-coding gene on chromosome 15 (75,258,334 to 75,273,455, forward strand). Ensembl gene ENSG00000167195.
Subcellular location (Human Protein Atlas): Vesicles; Centrosome; Nucleoplasm
Gene Ontology:
Biological process: Golgi organization
Cellular component: cis-Golgi network; Golgi cis cisterna; Golgi cisterna membrane; Golgi apparatus
Genetic constraint (gnomAD): Loss-of-function variants: 4 observed, 15.7 expected, observed/expected ratio (o/e) 0.25, 90% interval 0.12 to 0.58. The synonymous counts are far from expectation, so gnomAD's model fits this gene poorly and the ratio says little. Missense variants: 73 observed, 161.48 expected, observed/expected ratio (o/e) 0.45, 90% interval 0.37 to 0.55. Synonymous variants: 23 observed, 57.92 expected, observed/expected ratio (o/e) 0.4, 90% interval 0.28 to 0.56.
Homologues: Orthologues: mouse Golga2 (48% identical), dog GOLGA2 (45% identical), tropical clawed frog golga2 (35% identical), zebrafish golga2 (33% identical), Drosophila melanogaster GM130 (23% identical), Caenorhabditis elegans golg-2 (19% identical), rat Golga2l1 (5% identical). Paralogues in human: GOLGA6D (99% identical), GOLGA6B (99% identical), GOLGA6A (99% identical), GOLGA2 (55% identical), GOLGA8G (53% identical), GOLGA8F (52% identical), GOLGA8S (51% identical), GOLGA8N (49% identical), GOLGA8O (49% identical), GOLGA8Q (49% identical), GOLGA8T (48% identical), GOLGA8K (48% identical), and 6 more.
Diseases named in the same sentence as GOLGA6C in open-access papers:
GOLGA6C is named in the same sentence as 1 disease in open-access papers, as found by Europe PMC text mining. Sharing a sentence is not in itself a finding about the gene and the disease.
GOLGA6C shares sentences with these, for which no sentence is quoted: breast carcinoma (1 paper).